TNF (tumor necrosis factor)
Diseases named in the same sentence as TNF in open-access papers (continued):
Sharing a sentence is not in itself a finding about the gene and the disease.
colitis (continued). "Treatment of DSS colitis with s.c. administered hBD2 (0.1 mg/kg) resulted in a significant improvement of colitis; the therapeutic effect was superior to anti-TNF-α treatment." (PMID 32076420, 2020). "Intraperitoneal administration of the minor tobacco alkaloid and nicotinic receptor agonist anabaseine was shown to reduce tissue damage, myeloperoxidase activity, and colonic TNFα expression in a TNBS mouse model of colitis." (PMID 32855621, 2020). "A previous study demonstrated that treatment with orally administered live Parabacteroides distasonis dramatically improved the clinical parameters of acute colitis by decreasing the TNF-α production of macrophages." (PMID 32932871, 2020). "Exacerbation of mucosal damage by HFDs, particularly saturated fats (e.g., palm oil), is also reported in murine spontaneous ileitis (Mdr1a-/-), and colitis (e.g., Muc2-/-, TNFare; defective translational control of TNF mRNA)." (PMID 33603741, 2020). "The plant-derived alkaloid N-methylcytisine and the tea alkaloid theophylline mitigate colitis by downregulating TNFα, IL-1β, and IL-6 expression in DSS and acetic acid models of colitis, respectively." (PMID 32855621, 2020). "Sacral nerve stimulation promoted recovery of colitis demonstrated by decreased disease activity index, myeloperoxidase activity, tissue TNF‐alpha, and histological scores as well as an increased colonic M2 macrophage population." (PMID 31925899, 2020). "This study has analyzed the effect of Eleutherine palmifolia (L) Merr extract on colon histopathology, TNF-α expression, TGF-β level, and its hepatotoxicity on BALB/c mice of colitis-associated colon cancer model." (PMID 33369455, 2020). "Administration of apocynin, an antioxidant and a nonselective NADPH inhibitor, suppressed the inflammatory response in a model of DSS- and tumor necrosis factor-α-induced colitis." (PMID 33192516, 2020). "Further, oral administration of 6-shogaol, a representative active component of ginger, showed protective effects by regulating pro-inflammatory factors such as iNOS, TNF-α and IL-1β in dextran sulfate sodium-induced colitis and aspirin-induced gastric ulcer." (PMID 33066164, 2020). "Elevated levels of TNF-α, IL-1β, and IFNγ due to activation of immune cells are hallmarks of colitis, in both humans and mice." (PMID 32377161, 2020). "In this same colitis model, Avian-anti-TNF-α was compared with oral sulfasalazine (200 and 1000 mg/kg/day) or dexamethasone (2 mg/kg/day)." (PMID 32545207, 2020). "Tumor necrosis factor (TNF) is upregulated in the intestine of patients suffering from colitis after dual ipilimumab and nivolumab immunotherapy." (PMID 32226426, 2020). "Oral administration of berberine also ameliorates DSS-induced colitis and downregulates the expression of TNFα, IFNγ, KC, and IL-17 in colonic macrophages." (PMID 32855621, 2020). "The production of TNF-α, IL-1β, and IL-6 plays leading roles in the initiation and progression of colitis, and some of them have been regarded as a logical target for IBD therapy." (PMID 33363184, 2020). "For example, sanguinarine and cavidine suppress the expression of NF-κB p65 subunit, thereby reducing colonic TNFα and IL-6 in acetic acid-induced colitis." (PMID 32855621, 2020). "In an animal study, treatment with a strain of B. lactis was able to suppress COX-2 expression and colonic TNF-α production in a trinitrobenzene-sulfonic acid-induced model of rat colitis." (PMID 32218248, 2020). "The increased secretion of IL-1β, IL-6 and TNF-α has been demonstrated in experimental colitis models and in patients with IBD." (PMID 32971925, 2020). "In a study where 3% DSS (40 kDa) was administered for 7 days to induce acute colitis in C57BL/6 mice, serum TNF-α levels were quite high compared to control group, while IL-10 levels decreased in the colitis group." (PMID 31999939, 2020).
colitis (continued). "Plasma tumor necrosis factor alpha, Pentraxin 3, and malondialdehyde levels were significantly lower in the calcitriol administered colitis group than in the standard colitis group (p<0.01)." (PMID 32555936, 2020). "The subsequent induction and expression of various inflammatory cytokines (TNF-α, IL-6, IL1β, IL-17, and IFN-γ) and enzymes (iNOS and COX-2) that are associated with the initiation and development of colitis 49, 79 were also prevented by low-dose IL-2." (PMID 32308767, 2020). "It has been shown that TNF-α expression in the proximal colon is higher compared to the distal colon in DSS-induced colitis in mice." (PMID 32545207, 2020). "In previous study trials, for instance, oral delivery of anti-TNF Nanobody and IL-27-producing lactobacilli attenuated experimentally induced colitis in mice." (PMID 33584726, 2020). "Administration of exogenous vitamin D or a VDR agonist in IBD mouse models has been shown to reduce TNF-α and suppress colitis." (PMID 32555936, 2020). "The level of pro-inflammatory cytokines (TNFα, IL-1β and IL-6) in the blood serum, as well as IL-1β in the colon tissue of mice with colitis receiving algae extract, was lower than that of control animals (pronounced manifestations of colitis)." (PMID 32486405, 2020). "In animal study designs, B. lactis treatment was able to reduce iNOS synthase expression and colonic TNF-α production in a trinitrobenzene-sulfonic acid-induced model of rat colitis." (PMID 32218248, 2020). "KM1608 significantly attenuated the disease activity of dextran sodium sulfate-induced colitis in mice and suppressed inflammatory mediators such as myeloperoxidase, proinflammatory cytokines (TNF-α and IL-6), and the Th2-type cytokine IL-4 in the colon." (PMID 32927852, 2020). "Our model showed that bacteria colonization induced elevated detection of Th1 pro-inflammatory cytokines INF-γ, IL-6, and TNF-α, which have been previously suggested to create an inflammatory loop and worsen colitis in mice." (PMID 32444671, 2020). "As pro-inflammatory factors, IL-6, IL-17A, IL-23, and TNF-α are classical hallmarks of colitis, which induce the occurrence of colitis." (PMID 32581849, 2020). "Epicatechin has been shown to inhibit inflammation factors including TNF-α and IL-6 in mouse colitis and rat renal inflammation, while catechin can restrain the LPS-induced inflammation in BV-2 cells and human dental pulp cells." (PMID 32876071, 2020). "TNF-α, a cytokine with multiple effects that is produced by activated T cells, plays an essential role in the pathogenesis of colitis by triggering the accumulation and activation of leukocytes." (PMID 33299453, 2020). "Our data from the DSS model of colitis also suggest a complex role of TNFα and IL-6 in intestinal inflammation." (PMID 33144591, 2020). "In fact, inhibition in the production of TLR-4, NF-κB p65, COX-2, IL-17, TNF-α, IL-1β, and IL-6 is considered useful in treating colitis." (PMID 32848723, 2020). "We have recently shown in a colitis-induced CRC mouse model that ERβ in intestinal epithelial cells can downregulate the TNFα/NFkB signaling." (PMID 32999402, 2020). "Muscadine grapes or wine phytochemicals are capable to decrease MPO activity as well as colonic levels of IL-1β, IL-6, and TNF-α in experimental DSS-colitis." (PMID 32429359, 2020). "The novel formulation of anti-TNF-α antibodies administrated orally achieved high efficacy in the treatment of colitis mice compared with free antibodies administered orally." (PMID 32929381, 2020). "DSS-induced ulcerative colitis model has shown that TNF-α plays an important role in the progression of colitis." (PMID 31999939, 2020). "As DSS-induced colitis-like symptoms are reportedly accompanied by upregulation of pro-inflammatory cytokines, the plasma levels of IL-6, IL-1β, and TNF-α were examined." (PMID 32708415, 2020).
colitis (continued). "During the acute phase of colitis, plasma levels of IL-6 are increased, accompanied by activation of microglia, as well as increased levels of IL-1β, TNF-α, and p21 in the hippocampus." (PMID 32047521, 2020). "Since CD11b+ cells produced high amounts of TNF-α in the mucosa of DSS-treated mice, we targeted TNF-α in CD11b+ cells to improve colitis." (PMID 31968666, 2020). "indicate that active substances such as interleukin 1 (IL-1), tumor necrosis factor α (TNFα) and interferon γ (INFγ), which are extremely important in the inflammatory process of severe colitis, induce nitric oxide production." (PMID 33013401, 2020). "Administration of B-naphtoflavone, an AhR agonist, improved DSS-induced colitis in mice and downregulated colitis-induced pro-inflammatory cytokines such as TNFα, IL6 and IL1β mRNA." (PMID 32957545, 2020). "To assess the protective effect of NZ9000SHD-5 on DSS-induced colitis, we evaluated the protein levels and gene expression of common pro-inflammatory cytokines TNF-α, IL-6, and IL-1β in colon tissue." (PMID 32122364, 2020). "Similar galanin activity was found in chronic TNBS-induced colitis, but the impairment of neutrophil function, as well as the decrease in TNF-α level, was less pronounced." (PMID 33013401, 2020). "The levels of the proinflammatory cytokines IL1β, IL6 and TNF‐α are increased in both animal models of colitis and patients with UC." (PMID 32363766, 2020). "Based on the notion, we examined anti-IBD activity of various compounds against TNF-α-induced monocyte adhesion to colonic epithelial cells, an in vitro model of initial phase of colitis." (PMID 31619080, 2020). "Contrary to expectations, no activity of loganic acid in regard to inflammatory mediators was demonstrated in the TNBS-induced colitis model except for the TNF-α level decrease by combined LA and SA administration." (PMID 33299531, 2020). "Drinking water with soybean-derived tripeptide VPY can reduce DAI, weight loss, MPO activity, and expressions of IL-1β, IL-6, IL-17, IFN-γ, and TNF-α in colitis mice, suggesting that VPY can treat IBD." (PMID 32963495, 2020). "Synergistically, Rg3-RGE + PT inhibited expression of NO, iNOS, COX-2, IL-1β, IL-6, IL-5, IL-13, and TNF-α in the DSS-induced colitis mice’s macrophage cells, plasma, and colon tissue." (PMID 33182623, 2020). "Further, previous Korean study suggest the chelidonine ameliorates colon injury and inhibits the increase of inflammatory mediators, such as IL-6 and TNF-α, and oxidative damage in murine colitis model." (PMID 32612148, 2020). "Neutrally charged EPS from the putative probiotic Streptococcus thermophiles also decreased the production of the pro-inflammatory cytokines IFN-γ, IL-6, and TNF-α in DSS-induced colitis." (PMID 32351514, 2020). "The results showed that the supplemented mixture ameliorated colitis by reducing the expression levels of tumor necrosis factor (TNF)-α, interleukin (IL)-1β, and cyclo-oxygenase (COX)-2." (PMID 32995049, 2020). "The DSS treatment can increase the abundance of Clostridium species, which can induce TNF-α release and colitis." (PMID 33664740, 2020). "Demethyleneberberine, tetrandrine, and norisoboldine show protective effects in the DSS colitis model and reduce the levels of colonic IL-1β, TNFα, and phosphorylated NF-κB p65 subunit." (PMID 32855621, 2020). "In the TNBS mouse model of colitis, berberine reduces IFNγ, IL-1α, IL-6, IL-17, and TNFα expression in colonic tissues and sera and suppresses Th1 and Th17 cells through reduction of STAT1, STAT3, and NF-κB phosphorylation." (PMID 32855621, 2020). "Sulfobacin B, a type of sulfonolipid produced by O. splanchnicus, suppressed LPS-induced inflammatory responses in vitro and in vivo in a murine model of colitis by inhibiting dose-dependently LPS-stimulated production of TNF-α in cultured mouse macrophages." (PMID 33281770, 2020).
colitis (continued). "The average weight, colon length, and inflammatory factors in colon and serum of colitis mice after the treatment of novel formulation of anti-TNF-α antibodies even reached the similar level to healthy controls." (PMID 32929381, 2020). "It has been reported that an iridoid-rich fraction of Syringae folium extract possessed an anti-inflammatory effect against TNBS-induced colitis in rats through inhibiting proinflammatory cytokines (TNF-α, IL-6) by downregulating the expression of NF-κB." (PMID 33299531, 2020). "The NPs displayed potential effects in reducing TNF-α in a DSS-induced colitis model, both in vitro and ex vivo." (PMID 33316984, 2020). "For instance, green tea-derived polyphenol AcEGCG can protect against DSS-induced colitis by decreasing IL-1β, IL-6, TNF-α, and COX-2 productions and reducing NF-κB (p65 and IκBα) phosphorylation." (PMID 33664740, 2020). "Our study found that dietary TS ameliorated neutrophil accumulation in the colon of DSS-induced colitis mice which was accompanied with decreased TNF-α, IL-6, and IL-1β expression." (PMID 33363184, 2020). "Our earlier work identified TSP1 as the master substrate nucleating the combinatorial proteolytic MT1‐MMP program related to EC migration, invasion, and vessel formation in endothelial cells stimulated with TNFα, a crucial cytokine during colitis progression." (PMID 31793743, 2020). "Oral gavage of vancomycin or ampicillin significantly deteriorated tIsc-induced colitis; they dramatically increased colon shortening, myeloperoxidase activity, and TNF-α and IL-1β levels in the colon." (PMID 33324357, 2020). "The algae alkaloid caulerpin reduces DSS colitis by suppressing NF-κB activation and subsequently inhibiting the colonic production of TNFα, IFNγ, IL-6, IFNγ, and IL-17." (PMID 32855621, 2020). "The levels of IL-1β, IL-6, and TNF-α significantly increased after colitis was induced, and these levels were significantly reduced in the SASP, PCO, TCCO, and OO groups compared with the AA-alone group." (PMID 31936300, 2020). "This study evaluates colon histopathology, TNF-α, TGF-β, and hepatotoxicity on BALB/c mice colitis-associated colon cancer (CAC) model treated with EPE." (PMID 33369455, 2020). "Knockdown of PD-L1 in DSS murine colitis resulted in significant increase of TNF-α, whereas the levels of the cytokines IL-6, IL-2p70, IL-4, IFN-γ, and MCP-1 were comparable." (PMID 33271941, 2020). "GNE684 provided much the same level of protection as genetic inactivation of RIP1 in several inflammatory disease models (TNF-driven SIRS, colitis induced by NEMO deficiency in IECs, and collagen antibody-induced arthritis)." (PMID 31101885, 2020). "In a 2,4,6-trinitrobenzenesulphonic acid induced rat colitis model, the aqueous extract of P. edulis leaves reduced pro-inflammatory levels of IL-1β and TNF-α." (PMID 32508631, 2020). "Another study showed that two weeks of RJ administration led to changes in the serum levels of IL-1β, IL-10, and TNF-α in a rat model of colitis." (PMID 33050250, 2020). "Based on treatment approaches for primary autoimmune disorders, early treatment by anti-TNFα in colitis and plasma exchange in neurological toxicities have been advocated." (PMID 33064239, 2020). "Further experimental validation revealed that CSCC attenuated DSS-induced colitis by the suppression of the mRNA levels of IL-17A and of the cytokines it induces, such as IL-6, IL-1β, and TNF-α." (PMID 32382313, 2020). "In acute DSS-induced colitis mice, the expression of IL-6, TNF-α elevated, and microglia was activated in the brain tissue." (PMID 32047521, 2020). "In DSS-induced colitis, levels of the major pro-inflammatory cytokines including TNF-α, IL-17, and IFN-γ, were higher than those in the control and low-dose IL-2 groups (16K IU/day and 32K IU/day)." (PMID 32308767, 2020).
colitis (continued). "Colonic levels of the inflammatory cytokines TNF-α and IL-6 as markers of disease activity were measured by using western blot, which were significantly upregulated in the acute phase of colitis (day 7)." (PMID 31989391, 2020). "Soy-derived isoflavones have previously prevented colitis in a murine model and reduced the mRNA levels of TNF-α, IL-1β, IL-6, iNOS, and COX-2." (PMID 32708415, 2020). "Mice with macrophages deficient for UHRF1 manifest with TNF-α overexpression and aggravated DSS-induced colitis." (PMID 32848509, 2020). "XylB treatments reversed the imbalance between pro- (IL-1β, TNF-α, and IL-17A) and anti-inflammatory (IL-10) cytokines in experimental colitis." (PMID 32429359, 2020). "In both treatment cohorts, most patients with known disease location had extensive colitis or pancolitis (65% on vedolizumab vs 51% on anti-TNFα)." (PMID 32640990, 2020). "Study reveals that APS (200 mg/kg) treatment increases weight and colon length and reduces NF-κB DNA phosphorylation activity and down-regulates TNF-α, IL-1β, IL-6, IL-17 expressions associated with improvement in DSS-induced mice colitis." (PMID 32063999, 2020). "In a dextran-sulfate-induced colitis animal model, Yue and colleagues showed that the polysaccharides ameliorated the inflammatory response through lowering TNF-α, IL-1β, IL-6, and MPO activity and increased AMPK activity." (PMID 32560291, 2020). "The findings of the present study are indicative of the preventive ability of Cordia vignei leaf extract against the damaging effect of acetic acid-induced colitis in Sprague Dawley rats through inhibition of TNF-α and IL-6 activities." (PMID 32090060, 2020). "We found that severe colitis in aHPD-fed RAG2−/− mice is associated with high levels of homeostatic cytokine IL-33 and pro-inflammatory cytokines TNF-α and IL-6." (PMID 31105710, 2019). "These include colitis, which can be treated with anti-tumor necrosis factor (TNF) antibodies such as Infliximab." (PMID 31727152, 2019). "Our results showed that colitis mice had lower levels of IL-6 and TNF-α after Safranal treatment than 3.5% DSS-treated mice, suggesting that Safranal alleviated the severity of colitis by decreasing IL-6 and TNF-α in colon tissue." (PMID 31736758, 2019). "Lactobacillus plantarum CAU1055 had significantly reduced levels of TNF-α, and IL-6 in a dextran sulfate sodium-induced colitis animal model." (PMID 31921049, 2019). "It is highly interesting that in the models of acute and chronic DSS-induced colitis, TNFα exerts different functions, despite the fact that the same chemical agent to induce inflammation in both models was used." (PMID 30995806, 2019). "The patient demonstrated a rapid and profound tumor response to the combination immune checkpoint blockade, but developed a severe colitis that required high-dose intravenous corticosteroid and anti-TNFα therapy." (PMID 30791949, 2019). "IEC-specific VDR KO mice display worse colitis and higher expression of TNF-α, IL-1β, and MCP-1 than wild-type mice." (PMID 30804707, 2019). "Colitis induction increased serum IL-6, TNF-α, and IL-1β by 5-, 4.25-, and 1.9-fold, respectively in AA-colitis group in comparison to the NC group." (PMID 34466462, 2019). "JNJ-40346527 restored those pathways in TCT colitis toward normal similar to pathway restoration in CD patients responding to anti-TNFα therapy." (PMID 31710624, 2019). "Vedolizumab, an anti-integrin α4β7 antibody, should be considered in patients who develop colitis that is refractory to infliximab or in cases that anti-TNF- α therapy is contraindicated." (PMID 31293970, 2019). "It was confirmed by increased histopathology of colitis, goblet cell dysfunction, colonic dilatation and wall thickening, and increased serum levels of inflammatory cytokines (TNF-α and IL-10)." (PMID 31437166, 2019).